PRDX5 (peroxiredoxin 5)
Description:
Thiol-specific peroxidase that catalyzes the reduction of hydrogen peroxide and organic hydroperoxides to water and alcohols, respectively. Plays a role in cell protection against oxidative stress by detoxifying peroxides and as sensor of hydrogen peroxide-mediated signaling events.
Synonyms: AOEB166; Prx-V; ACR1; SBBI10; MGC142285; PRXV; PMP20; B166; PRDX6; PLP; MGC117264; MGC142283; HEL-S-55
Tractability: Small molecule: a structure with a bound ligand is known; it has a high-quality binding pocket. PROTAC: ubiquitination databases record sites on it; its protein half-life has been measured.
Target class: Enzyme; Oxidoreductase
Gene: Protein-coding gene on chromosome 11 (64,318,041 to 64,321,822, forward strand). Ensembl gene ENSG00000126432.
Subcellular location: Mitochondrion (Isoform Mitochondrial); Cytoplasm (Isoform Cytoplasmic+peroxisomal); Peroxisome matrix
Subcellular location (Human Protein Atlas): Mitochondria
Pathways (Reactome):
Cellular responses to stimuli: Detoxification of Reactive Oxygen Species
Gene Ontology:
Molecular function: cysteine-type endopeptidase inhibitor activity involved in apoptotic process; peroxidase activity; protein binding; RNA polymerase III transcription regulatory region sequence-specific DNA binding; thioredoxin peroxidase activity; thioredoxin-dependent peroxiredoxin activity; oxidoreductase activity
Biological process: cellular response to reactive oxygen species; negative regulation of apoptotic process; negative regulation of transcription by RNA polymerase III; response to oxidative stress; cell redox homeostasis; cellular response to oxidative stress; hydrogen peroxide catabolic process; inflammatory response; cellular oxidant detoxification
Cellular component: cytoplasm; cytoplasmic vesicle; cytosol; extracellular exosome; extracellular region; intracellular membrane-bounded organelle; mitochondrion; nucleus; perinuclear region of cytoplasm; peroxisomal matrix; peroxisome; mitochondrial matrix
Genetic constraint (gnomAD): Loss-of-function variants: 20 observed, 23.5 expected, observed/expected ratio (o/e) 0.85, 90% interval 0.6 to 1.24. The upper end of that interval is the gene's LOEUF score, 1.24, which puts it in group 5 of 6, group 1 being the genes least tolerant of losing a copy. Missense variants: 200 observed, 234.32 expected, observed/expected ratio (o/e) 0.85, 90% interval 0.76 to 0.96. Synonymous variants: 87 observed, 94.77 expected, observed/expected ratio (o/e) 0.92, 90% interval 0.77 to 1.1.
Homologues: Orthologues: chimpanzee PRDX5 (99% identical), macaque PRDX5 (95% identical), guinea pig PRDX5 (78% identical), mouse Prdx5 (76% identical), dog PRDX5 (74% identical), pig PRDX5 (69% identical), rat Prdx5 (68% identical), tropical clawed frog prdx5 (51% identical), zebrafish prdx5 (47% identical), Drosophila melanogaster Prx5 (46% identical).
Diseases named in the same sentence as PRDX5 in open-access papers:
PRDX5 is named in the same sentence as 149 diseases in open-access papers, as found by Europe PMC text mining. Sharing a sentence is not in itself a finding about the gene and the disease. The quoted sentences say what the papers report.
breast carcinoma (24 papers, 2007 to 2025). "In breast cancer, Prdx5 is upregulated in the mammary tissues and it is associated with poor prognosis." (PMID 31500275, 2019). "In breast cancer, PRDX5 interacts with the tumor-suppressor BRCA2 silencer, thereby increasing BRCA2 expression under oxidative stress situations." (PMID 40597205, 2025). "Increased levels of Prdx5 proteins were found in several aggressive cancer types, such as ovarian carcinoma, Hodgkin’s lymphoma, breast carcinoma, or thyroid cancer." (PMID 37443747, 2023). "GATA1 is also a promoter binder factor of peroxiredoxin 5 in human breast cancer cells through inhibiting apoptosis." (PMID 30872657, 2019). "This implies that GATA1-regulated Prdx5 transcription can be targeted to treat breast cancer, but it requires further analysis involving the overexpression of GATA1 and its effects on tumor production and metastasis." (PMID 31500275, 2019). "GATA1 transcription factor binds to the promoter region of Prdx5 in breast cancer cells and downregulates the transcription of Prdx5." (PMID 31500275, 2019). "In patients with breast cancer, increased expression of PRDX5 was found to be significantly correlated with a shorter patient survival." (PMID 30104402, 2018). "Furthermore, cathepsin D and peroxiredoxin-5 have been found to be upregulated in breast cancer cell lines in response to radiation therapy." (PMID 29068423, 2017). "The molecular docking was carried out on the active site of human peroxiredoxin 5 (PDB code 1HD2, alpha estrogen receptor alpha (ERα; PDB: 5GS4) and pirin inhibiting target [PDB: 3ACL] for antioxidant study, breast cancer and skin cancer cell lines respectively using Auto dock vina program." (PMID 39687105, 2024). "Moreover, in the case of control samples, we found overexpression of the proteins: PRDX2, PRDX5 and AIFM1 involved in ROS; TUSC2 in PMM; ALKBH7, RHOT1, SAMM50, IMMT and HSPA9 in the MMO; and FUNDC2 in MIT compared to luminal A and basal-like breast cancer tumors." (PMID 35327574, 2022). "Different methods and different samples had been used in the two studies and our study, while there are four genes (PGK1, GCN1L1, PRDX5, and SDHD) that were repeated and identified at least twice in three studies and might become valuable prognostic tools or therapeutic targets in breast cancer." (PMID 26576432, 2015). "In human breast cancer, GATA1 as a negative transcriptional regulator binds the Peroxiredoxin 5 (Prx5) gene, and overexpression of Prx5 in mammary tissue is associated with the inhibition of apoptosis and poor prognosis." (PMID 24564526, 2014). "Karihtala and colleagues observed that staining for PRDX2 and PRDX6 was negative in half of breast cancer cases, whereas PRDX1, PRDX3, PRDX4 and PRDX5 showed stronger expression levels." (PMID 17980029, 2007).
lung carcinoma (17 papers, 2016 to 2026). "Prdx5 deficiency in macrophages promotes lung cancer progression and M2-like polarization." (PMID 40223093, 2025). "It is possible that alteration of PRDX5 can benefit cancer management from other angles; knockdown of PRDX5 sensitizes non‐small cell lung cancer cells to cisplatin, as well as inhibits cancer cell growth in zebrafish model." (PMID 40831323, 2025). "In line with this, in humans, an increase in the centromeric αSat and HSat3 transcripts was detected in a study that encompasses the knockdown of peroxiredoxin-5 (PRDX5), an antioxidant protein that neutralizes ROS in human lung cancer cells." (PMID 38254724, 2024). "In contrast to aggressive and fast-growing tumor types, such as lung adenocarcinoma, a previous study demonstrated variations in Prdx5 mRNA levels as prognostic factors in lung cancer, with low levels of Prdx5 correlating with poor overall survival." (PMID 37443747, 2023). "The zebrafish models mainly investigated the synergistic effects of PRDX5 and Nrf2 on lung cancer drug resistance under oxidative stress." (PMID 37305326, 2022). "In the present study, PRDX5 knockdown enhanced the effect of PAM on A549 lung cancer cells via the MAPK signaling pathway." (PMID 35546738, 2022). "To characterize PAM-induced apoptosis after the knockdown of PRDX5 in A549 lung cancer cells, we determined the expression levels of the important proteins of the MAPK pathway." (PMID 35546738, 2022). "PRDX5 knockdown significantly inhibited cell colony formation and migration, increased ROS accumulation, and reduced mitochondrial membrane potential in lung cancer cells." (PMID 35546738, 2022). "Meanwhile, in the zebrafish models, PRDX5 and Nrf2 have significant regulatory impacts on lung cancer progression and drug resistance activities under oxidative stress." (PMID 37305326, 2022). "The use of an appropriate conditional PAM for its lethal effect on lung cancer cells is considered reasonable, and this effect was confirmed via PRDX5 knockdown." (PMID 35546738, 2022). "To study the role of PRDX5 in PAM-mediated induction of apoptosis in A549 lung cancer cells, we evaluated the suppression of PRDX5 via western blotting using anti-PRDX5 antibodies." (PMID 35546738, 2022). "To further elucidate the role of Nrf2 in NSCLC tumorigenesis, we identified PRDX5 (Peroxiredoxin 5) as a novel binding partner for Nrf2 through immunoprecipitation in tissues and lung cancer cells." (PMID 31899687, 2020). "An upregulated expression of Prdx3 and Prdx5 has been reported in different cancer types, such as breast, ovarian, endometrial, and lung cancers, as well as in Hodgkin’s lymphoma and hepatocellular carcinoma." (PMID 31500275, 2019). "PRDX5 plays a protective role in against oxidative stress by reducing apoptosis in human tendon cells and lung carcinoma cells." (PMID 27121020, 2016). "Therefore, PRDX5 expression is likely to be regulated during apoptosis in A549 lung cancer cells treated with PAM." (PMID 35546738, 2022). "As the previous experiment showed that PRDX5 expression decreased in PAM-treated A549 lung cancer cells, we constructed a A549 PRDX5 knockdown cell line, in which the expression level of PRDX5 decreased after PAM treatment while the expression levels of the remaining PRDXs were maintained." (PMID 35546738, 2022). "Hence, PRDX5 knockdown combined with PAM treatment represents an effective option for lung cancer treatment." (PMID 35546738, 2022). "In addition, there is evidence that Prdx5 is also involved in chemoresistance to adriamycin, bleomycin, vinblastine, and dacarbazine in patients of Hodgkin’s lymphoma and in vitro lung carcinoma U1810 cell lines." (PMID 31500275, 2019). "As not all lung cancer patients have shown such ROS-mediated hypomethylation, driver mutations also need to be considered in further studies to find additional regulatory mechanisms for Prdx5 expression." (PMID 37443747, 2023).
lung carcinoma (continued). "Meanwhile, PRDX5-Nrf2 significantly regulates NSCLC progression and drug resistance activities in the lung cancer zebrafish models." (PMID 37305326, 2022). "Our data showed that PRDX5 knockdown and PAM treatment induced ROS generation, downregulated the anti-apoptotic protein BCL2, disrupted the MMP, and enhanced apoptosis in A549 lung cancer cells." (PMID 35546738, 2022). "The mRNA levels of PRDX1, PRDX2, PRDX3, PRDX5, and PRDX6 showed an excellent correlation with the OS of lung cancer patients." (PMID 32908916, 2020).
gastric cancer (14 papers, 2016 to 2025). A primary or metastatic malignant neoplasm involving the stomach. "For instance, it was recently reported that PRDX5 overexpression leads to EMT phenotype in gastric cancer." (PMID 40597205, 2025). "Studies have shown that PRDX5 protects gastric cancer cells from apoptosis by reducing intracellular ROS accumulation, thus promoting their proliferation and invasiveness." (PMID 40281661, 2025). "PRDX5 is elevated and drives tumorigenic phenotype in colon cancer, non-small cell lung cancer, and gastric cancer." (PMID 35350568, 2022). "In gastric cancer, overexpression of PRDX5 alters the epithelial to mesenchymal transition (EMT) mechanism, with a poor prognosis for patients being correlated." (PMID 33049715, 2020). "The expression of Prdx5 is closely related to the tumor size, depth, and lymphatic invasion in patients suffering from gastric cancer." (PMID 31500275, 2019). "They suggested that high levels of PRDX5 enhance carcinogenicity and contribute to poor prognosis of gastric cancer." (PMID 30104402, 2018). "An anticancer bioactive peptide (ACBP), goat peroxiredoxin-5 (gPRDX5), was identified from goat-spleen extract after immunizing the goat with gastric cancer-cell lysate." (PMID 27074889, 2016). "Moreover, the enhanced expression of Prdx5 leads to augmented carcinogenicity by increasing the proliferation and invasiveness of gastric cancer cells through the upregulation of Snail." (PMID 31500275, 2019). "In addition, silencing of PRDX5 and PDGF-B suppressed the proliferation of gastric cancer cells in vitro." (PMID 28423550, 2017).
ovarian carcinoma (12 papers, 2018 to 2025). A malignant neoplasm originating from the surface ovarian epithelium. "Certain types of PRDX, such as PRDX5, relate to progression of carcinogenic tumors and are overexpressed in cases of endometrial and ovarian cancer." (PMID 32887897, 2020). "Our results showed that high PRDX5 expression was associated with poorer OS for serous ovarian cancer patients, endometrioid ovarian cancer patients, and grade II or III ovarian cancer patients." (PMID 30104402, 2018). "Further studies revealed that high PRDX5 mRNA expression was associated with a poor PFS in stages III and IV ovarian cancer patients." (PMID 30104402, 2018). "Meanwhile, images of tissue staining by IHC showed that stroma cells had negative PRDX5 expression in normal ovarian tissues; however, there were 1 case of high, 9 cases of medium and 1 case of low PRDX5 staining among 12 cases of ovarian cancer tissues examined." (PMID 30104402, 2018). "Furthermore, increased mRNA expression of PRDX5 was found to be correlated with a poorer OS in grade II or III ovarian cancer patients and a poorer PFS in grade II ovarian cancer patients." (PMID 30104402, 2018). "Elevated expression of PRDX3, PRDX5, and PRDX6 mRNAs showed poorer overall survival (OS); PRDX5 and PRDX6 also predicted poor progression-free survival (PFS) for ovarian cancer patients." (PMID 31315664, 2019). "Using the KM plotter database, we explored the correlation of PRDX5 mRNA levels to OS and PFS of 1816 ovarian cancer patients." (PMID 30104402, 2018). "Elevated PRDX5 mRNA expression was correlated with poorer OS and PFS in all ovarian cancer patients treated with Platin, Taxol, and Taxol+Platin chemotherapy." (PMID 30104402, 2018). "According to our results, high levels of PRDX3, PRDX5, and PRDX6 indicated poor clinical outcomes in ovarian cancer." (PMID 30104402, 2018). "Meanwhile, elevated expression of PRDX3, PRDX5, and PRDX6 mRNAs showed poorer overall survival (OS); PRDX5 and PRDX6 also predicted poor progression-free survival (PFS) for ovarian cancer patients." (PMID 30104402, 2018). "Mitochondrial Prdxs are overexpressed in ovarian cancer cells, and Prdx5 serves as a negative predictor of survival in patients suffering from ovarian cancer." (PMID 31500275, 2019). "Moreover, we observed that PRDX5 overexpression was related to unfavorable OS and PFS in all ovarian cancer patients treated with Platin, Taxol, and Taxol+Platin chemotherapy." (PMID 30104402, 2018). "Furthermore, PRDX5 also predicted poor PFS for all ovarian cancer patients, endometrioid ovarian cancer patients, grade II ovarian cancer patients, and stages III and IV ovarian cancer patients." (PMID 30104402, 2018). "In the current study, HPA database outcomes showed that the expression of PRDX5 protein was elevated in ovarian cancer tissues, which was completely not detected in normal ovarian tissues." (PMID 30104402, 2018). "Taken together, these observations indicated that PRDX3, PRDX5, and PRDX6 overexpression could lead to the chemotherapy resistance in ovarian cancer and therapeutic strategies targeting these isoforms may therefore be an effective anticancer therapy for ovarian cancer." (PMID 30104402, 2018). "Last but not least, there is no available research about the exact function of PRDX5 and PRDX6 in BrCa, but overexpression of PRDX5 and prognostic values have been observed in numerous cancers, including ovarian cancer and endometrial cancer." (PMID 31402980, 2019).
colon carcinoma (11 papers, 2015 to 2024). "We performed ChIPseq using HCT116 colon carcinoma cells, identifying ~850 putative target genes associated with metabolism (e.g., Prdx5, Mdh1, Ahcy), transcription (Taf12, Tet2, histones), malignancy (Met, Blcap, Rras, Jag1, Gsk3a) and mitotic stability (Zbtb4)." (PMID 31059499, 2019). "Conversely, the protein expression of PRDX5 and PRDX6 was lower in colon cancer tissues." (PMID 36969053, 2023).
colorectal cancer (7 papers, 2023 to 2026). A primary or metastatic malignant neoplasm that affects the colon or rectum. "Okanin is a promising candidate drug, and PRDX5 can serve as a drug target for the chemotherapeutic development of treatments of malignancies, including colorectal cancer." (PMID 40831323, 2025). "We found that okanin in vitro and in vivo inhibited the growth of colorectal cancer cells by directly targeting at PRDX5 to trigger both apoptosis and ferroptosis, suggesting that PRDX5 is a target of cancer chemotherapy." (PMID 40831323, 2025). "In xenograft mouse models, PRDX5 overexpression has been shown to promote tumor growth of colorectal cancer cells." (PMID 40281661, 2025). "Okanin suppresses colorectal cancer growth by directly targeting PRDX5." (PMID 40831323, 2025). "Both FKB prolyl isomerase 1B (FKBP1B) and peroxiredoxin 5 (PRDX5) had higher plasma levels in lung- and colorectal cancer as compared to all the other cancers and were also selected independently by the models for both of these cancer types." (PMID 37463882, 2023). "PRDX5 and GPX4 are candidate targets for cancer chemotherapy, at least for colorectal cancer." (PMID 40831323, 2025). "We assessed the importance of mitochondrial ROS for tumor cell proliferation, survival, and for tumor xenograft growth by stably expressing a hydrogen peroxide (H2O2) scavenger, peroxiredoxin-5, in the mitochondrial IMS (IMS-Prdx5) in 143B osteosarcoma and HCT116 colorectal cancer cell lines." (PMID 36935009, 2023).
hepatocellular carcinoma (7 papers, 2015 to 2024). A malignant tumor that arises from hepatocytes. "This suggests that PRDX5 regulates β-CCE-induced apoptosis in hepatoma cells." (PMID 36118528, 2022).
Obesity (7 papers, 2020 to 2023). Accumulation of substantial excess body fat. "Prdx5 deficiency increases the susceptibility to high-fat diet-induced obesity and metabolic abnormalities." (PMID 36735291, 2023). "Interestingly, we found a significant upregulation with PRDX5, which is consistent with the notion that the cells of individuals with obesity try to deal with excess H2O2." (PMID 38004202, 2023). "Furthermore, our study observed several differentially regulated EFP proteins in the AE group that can mitigate diet-induced obesity, such as the upregulated PRDX5 as well as the downregulated LAMA4, S27A1, and HS12A, as reported in previous studies." (PMID 36982812, 2023). "Obesity negatively impacted the sWAT-MSC secretome, since its anti-oxidant (GCL, Prdx5, Prdx6) and tissue development (Ang, Angptl4, Fstl3, Pgf) activities were lost, while factors promoting osteoporosis and negative vessel remodeling were acquired." (PMID 32727501, 2020). "Obesity negatively impacted sWAT-MSC secretome: the anti-oxidant (GCL, Prdx5, Prdx6) and tissue development (Ang, Angptl4, Fstl3, Pgf) activities were lost, while factors promoting osteoporosis and negative vessel remodeling were acquired." (PMID 32727501, 2020).